ALKBH8 (alkB homolog 8, tRNA methyltransferase)
Description:
Catalyzes the methylation of 5-carboxymethyl uridine to 5-methylcarboxymethyl uridine at the wobble position of the anticodon loop in tRNA via its methyltransferase domain. Catalyzes the last step in the formation of 5-methylcarboxymethyl uridine at the wobble position of the anticodon loop in target tRNA. Has a preference for tRNA(Arg) and tRNA(Glu), and does not bind tRNA(Lys). Binds tRNA and catalyzes the iron and alpha-ketoglutarate dependent hydroxylation of 5-methylcarboxymethyl uridine at the wobble position of the anticodon loop in tRNA via its dioxygenase domain, giving rise to 5-(S)- methoxycarbonylhydroxymethyluridine; has a preference for tRNA(Gly). Required for normal survival after DNA damage. May inhibit apoptosis and promote cell survival and angiogenesis.
Synonyms: ABH8; MGC10235; TRM9; TRMT9A; MRT71; TRMT9
Tractability: Small molecule: a structure with a bound ligand is known; it has a high-quality binding pocket. PROTAC: ubiquitination databases record sites on it; its protein half-life has been measured.
Gene: Protein-coding gene on chromosome 11 (107,502,727 to 107,565,742, reverse strand). Ensembl gene ENSG00000137760.
Subcellular location: Cytoplasm; Nucleus
Subcellular location (Human Protein Atlas): Nucleoplasm; Microtubules; Mitotic spindle; Primary cilium
Pathways (Reactome):
Metabolism of RNA: tRNA modification in the nucleus and cytosol
Gene Ontology:
Molecular function: protein binding; tRNA (5-carboxymethyluridine(34)-5-O)-methyltransferase activity; tRNA (uridine) methyltransferase activity; tRNA binding; zinc ion binding; iron ion binding; 2-oxoglutarate-dependent dioxygenase activity; methyltransferase activity; nucleic acid binding; RNA binding; S-adenosylmethionine-dependent methyltransferase activity; transition metal ion binding
Biological process: DNA damage response; tRNA methylation; tRNA wobble uridine modification
Cellular component: cytoplasm; cytosol; nucleoplasm; nucleus; tRNA methyltransferase complex
Genetic constraint (gnomAD): Loss-of-function variants: 27 observed, 46.7 expected, observed/expected ratio (o/e) 0.58, 90% interval 0.43 to 0.8. The upper end of that interval is the gene's LOEUF score, 0.8, which puts it in group 3 of 6, group 1 being the genes least tolerant of losing a copy. Missense variants: 680 observed, 720.19 expected, observed/expected ratio (o/e) 0.94, 90% interval 0.89 to 1.01. Synonymous variants: 242 observed, 248.32 expected, observed/expected ratio (o/e) 0.97, 90% interval 0.88 to 1.08.
Homologues: Orthologues: chimpanzee ALKBH8 (98% identical), macaque ALKBH8 (97% identical), pig ALKBH8 (84% identical), dog ALKBH8 (83% identical), mouse Alkbh8 (77% identical), rat Alkbh8 (77% identical), tropical clawed frog alkbh8 (58% identical), zebrafish alkbh8 (57% identical), Drosophila melanogaster CG17807 (41% identical), Caenorhabditis elegans alkb-8 (33% identical). Paralogues in human: TRMT9B (17% identical), ALKBH6 (8% identical).
Diseases named in the same sentence as ALKBH8 in open-access papers:
ALKBH8 is named in the same sentence as 22 diseases in open-access papers, as found by Europe PMC text mining. Sharing a sentence is not in itself a finding about the gene and the disease. The quoted sentences say what the papers report.
bladder cancer (7 papers, 2018 to 2026). "In addition, human alkylated DNA repair protein alkB homolog 8 (ALKBH8) is reported to be associated with the tumorigenesis of bladder cancer." (PMID 36289714, 2022). "ALKBH8 also promotes the growth of bladder cancer by regulating survivin expression, but its relationship with tRNA levels has not been confirmed." (PMID 41501031, 2026). "It has been reported both in vitro and in vivo that ALKBH8 promotes the expansion, survival and invasion of bladder cancer." (PMID 32241281, 2020). "Silencing of ALKBH8 also significantly inhibited the invasion, angiogenesis, and growth of bladder cancer cells by downregulating the protein expression of survivin, an anti-apoptotic factor, which is upregulated in bladder cancer." (PMID 37007161, 2023). "Another example is ALKBH8, which is crucial in bladder cancer transformation." (PMID 32241281, 2020).
urothelial carcinoma (2 papers, 2011). A malignant neoplasm derived from the transitional epithelium of the urinary tract (urinary bladder, ureter, urethra, or renal pelvis). "ALKBH2 and ALKBH3 share the ability of E.coli AlkB to directly reverse nucleic acid damage in vitro, and we reported in a recent study that ALKBH8 has important roles in the survival and progression of human urothelial carcinoma both in vitro and in vivo." (PMID 21285982, 2011). "Previously, we showed that a novel isoform of the DNA repair enzyme ALKBH, ALKBH-8, contributes to progression of urothelial carcinoma cells via NOX1-ROS signal-mediated resistance to apoptosis induction." (PMID 22032647, 2011). "Recently, we identified generation of intracellular hydrogen peroxide by NOX1 as a major downstream signal for a novel human AlkB homologue, ALKBH-8, that contributes to cell survival by enhancing resistance to apoptosis in human urothelial carcinoma cells, both in vitro and in vivo." (PMID 22032647, 2011).
behavioral disorder (1 paper, 2024). "In our behavioral examinations of Alkbh8−/− mice, no severe behavioral disorder or pronounced phenotypic change was observed." (PMID 38550277, 2024).
breast carcinoma (1 paper, 2022). "It is short of direct proof about the relationship between ALKBH family and stage or subclasses in breast cancer, this study provided that ALKBH1, ALKBH4, and ALKBH6 might be associated with later stage, while ALKBH8 was relative to an earlier stage." (PMID 35980268, 2022). "With compared the expression of ALKBH family members in breast cancer and normal samples, the up-regulation was ALKBH1, ALKBH2, ALKBH4, ALKBH6, ALKBH7, and others such as ALKBH3, ALKBH8, FTO was down-regulation." (PMID 35980268, 2022). "As the data shown, the OS of breast cancer patient was significant difference when gene expression was changed in ALKBH3 (p=0.00063), ALKBH4 (p=0.013), ALKBH7 (p=0.0025), ALKBH8 (p=0.00013) and FTO (p=0.045)." (PMID 35980268, 2022).
gastric cancer (1 paper, 2024). A primary or metastatic malignant neoplasm involving the stomach. "However, ALKBH8 was highly expressed in only six pairs of gastric cancer tissues, while ALKBH4 was highly expressed in seven pairs, and FTO was highly expressed in all 10 pairs." (PMID 38902235, 2024). "We found that in 10 pairs of human gastric cancer and normal tissues, ALKBH1, ALKBH4, ALKBH8, and FTO were highly expressed in the gastric cancer tissues." (PMID 38902235, 2024).
generalized epilepsy (1 paper, 2025). Epilepsy that is characterized by generalized seizure types and may have typical interictal and/or ictal EEG findings that accompany generalized seizure types (for example generalized spike-wave). "A homozygous deleterious variant in ALKBH8 (Ser96Phe) (VUS) was found in EPBL-0022, a 10 year old female who presented with generalized epilepsy and GDD and diagnosed with Lennox–Gastaut syndrome." (PMID 40565278, 2025).
lymph node metastasis (1 paper, 2021). "Conversely, the expression levels of ALKBH5, ALKBH8 and FTO were lower than those in normal tissues at any stage of lymph node metastasis." (PMID 34150745, 2021).
viral infection (1 paper, 2025). "To validate these findings and identify specific components of the modification pathway that are essential for viral infection, we performed shRNA targeted knockdowns of ALKBH8 and CTU1." (PMID 40806605, 2025). "Downstream U34 modification enzymes, ALKBH8 and CTU1, are essential for both SARS-CoV-2 and ZIKV replication—According to the U34 modification pathway, alteration of the two enzymatic steps downstream of the Elongator complex (ELP1-6) step to generate mcm5s2U would also affect viral infection." (PMID 40806605, 2025).
ZIKV infection (1 paper, 2025). "ShRNAs targeting ALKBH8 and CTU1 both led to a significant reduction in SARS-CoV-2 and ZIKV infection levels compared to cells treated with the control shRNA (IRV1)." (PMID 40806605, 2025). "We used an shRNA-based approach to examine the role of ALKBH8 and CTU1, key enzymes acting downstream of Elongator in the U34 pathway, in SARS-CoV-2 and ZIKV infection." (PMID 40806605, 2025). "Specifically, ALKBH8 and CTU1 knockdowns both resulted in an approximately 60% reduction in SARS-CoV-2 infection and a 90–95% reduction in ZIKV infection." (PMID 40806605, 2025).
tumor (12 papers, 2012 to 2026). "Several members of the ALKBH family, such as ALKBH2 and ALKBH8, are strongly associated with tumor progression by inducing apoptosis resistance and regulating proinflammatory signaling and EMT." (PMID 34638302, 2021). "Altered Alkbh8 expression has been implicated in cancer etiology, as abnormally high Alkbh8 expression is associated with an aggressive cancer phenotype, tumor angiogenesis and metastasis." (PMID 26147969, 2015). "In contrast to parental, LacZ- or GFP-expressing SW620 cells, re-expression of hTRM9L, yTrm9 or Alkbh8 caused a dramatic inhibition of SW620 tumour growth on CAMs." (PMID 23381944, 2013). "In addition, ALKBH8 is abnormally expressed in various cancers, and its function is closely related to tumor progression." (PMID 41501031, 2026). "The proteins coded by ALKBH8 and Trm9 are enzymes that catalyze the swing of tRNA, playing important roles in oxygen pressure regulation, DNA damage repair and cell pressure signal regulation in tumor cells 9,10." (PMID 37056382, 2023). "On account of the advance stage which indicates progression, ALKBH1, ALKBH4, ALKBH6, and ALKBH8 may be the potential biomarker for predicting tumor progression." (PMID 35980268, 2022). "It has been proposed that an intravesical injection of ALKBH8 siRNA may reverse the invasive character of the neoplasm in patients." (PMID 32241281, 2020). "Therefore, significant future studies will involve aging and exposure studies of Alkbh8-/- mice to determine tumor rates relative to wild-type mice." (PMID 26147969, 2015). "For example, TRIT1 and ALKBH8 functions are deeply related as mcm5U have been described as i6A dependent, although they are described as a tumor suppressor and oncogene respectively, some hypotheses exist as other functions of the genes but more research are needed to clarify it." (PMID 32241281, 2020). "In the case of ALKBH8, its activity promotes the production of low ROS amounts by NOX-1, therefore contributing to oncogenic ROS signaling and tumor progression towards an invasive phenotype." (PMID 34638302, 2021). "Of these tumor-specific pathways, some pathways such as the tRNA aminoacylation pathway, STAT5 pathway, and ALKBH8 pathway, have been reported to contribute to cancer progression in various cancers." (PMID 34210306, 2021).
cancer (10 papers, 2013 to 2026). A tumor composed of atypical neoplastic, often pleomorphic cells that invade other tissues. "This function may be linked to cancer cell progression as ALKBH8 has been found to be upregulated in bladder cancer and increase ROS production in cancer cells." (PMID 35721477, 2022). "Our results in MEFs predict that Alkbh8-/- mice will have an increased sensitivity to ROS inducing agents and may be predisposed to develop diseases linked to aberrant ROS production (i. e., neurodegenerative and inflammatory diseases or cancer)." (PMID 26147969, 2015). "ALKBH8 expression is also significantly altered in other cancers, such as glioma, suggesting its potential role in tumorigenesis and drug resistance." (PMID 41501031, 2026). "In conclusion, we have defined a mechanistic role for Alkbh8 in the oxidative stress response, which has implications for cancer development and other pathologies arising from defective anti-oxidant and redox cycling defenses." (PMID 26147969, 2015). "ALKBH8 is a methyltransferase that can affect codon-specific translation by modulating tRNA modifications, thereby influencing the occurrence and development of cancer." (PMID 41501031, 2026). "In summary, ALKBH8 affects the ROS detoxification network and protein translation by regulating tRNA modification, thereby influencing the occurrence and development of cancer." (PMID 41501031, 2026). "In the broader scheme of cellular signaling, Alkbh8 represents a new link between translation-based regulatory mechanisms (i. e., stop codon reprogramming) and stress responses, with likely implications in cancer." (PMID 26147969, 2015). "In addition, ALKBH8, the methyltransferase implicated in the final step of mcm5s2U and mcm5U formation is highly expressed in bladder cancer and ALHBH8 knockdown induces cancer cell death due to reduced expression of the anti-apoptotic protein survivin." (PMID 30597914, 2018). "In addition to upregulation of Elongator, ALKBH8 and thiolase genes CTU1 and CTU2 genes, other tRNA modification genes, including NSUN2 (m5C) and METTL1 (m 7G) also become overexpressed in human cancers." (PMID 30597914, 2018).
neurological disorders (4 papers, 2024 to 2025). "Mutations in the six subunits of Elongator, and Alkbh8 is associated with human neurological diseases." (PMID 39705244, 2024). "Loss of ALKBH8 can result in neurological disorders and dysregulated oxidative stress responses." (PMID 40128671, 2025). "Several clinical cases indicate that mutations in the mcm5s2U34 modifying enzymes, like Elongator subunits (ELP2, ELP4, and ELP6), ALKBH8 and CTU2, are associated with human neurological diseases." (PMID 39705244, 2024). "Further elucidation of the functional mechanism of ALKBH8 is expected to contribute to the understanding of the physiological functions of the central nervous system and the pathophysiology of neurological disorders, such as ID." (PMID 38550277, 2024).
ALKBH8 also shares sentences with these, for which no sentence is quoted: Intellectual disability (3 papers); colorectal cancer (1); developmental delay (1); epilepsy (1); Hyporeflexia (1); infection (1); ischaemic stroke (1); leukaemias (1); Obesity (1); Stroke (1).